VEGFA (vascular endothelial growth factor A)
Diseases named in the same sentence as VEGFA in open-access papers (continued):
Sharing a sentence is not in itself a finding about the gene and the disease.
myelofibrosis (6 papers, 2011 to 2025). A partial or complete replacement of the bone marrow stroma by fibrous tissue. "Allele frequency and frequency of the genotypes of the rs3025039 VEGFA single nucleotide variation (SNV) in the myelofibrosis‐type megakaryocyte dysplasia (MTMD) stratified for the phenotypic variants and comparison with normal control subjects." (PMID 37601859, 2023). "Past studies revealed that STAT3, VEGFA, and TNF also played an important role in the pathogenesis of myelofibrosis." (PMID 30622613, 2018).
pregnancy-induced hypertension (6 papers, 2014 to 2023). "Changes in endometrial levels of many angiogenic growth factors have been observed in pregnancy-induced hypertension (PIH), including vascular endothelial growth factor A (VEGF-A) and placental growth factor (PIGF)." (PMID 33652665, 2021).
Pruritus (6 papers, 2020 to 2023). Pruritus is an itch or a sensation that makes a person want to scratch. "The mechanism of WZLYW in pruritus may be regulating VEGFa expression." (PMID 36611103, 2023).
abortion (5 papers, 2014 to 2025). the ending of pregnancy by removing a fetus or embryo before it can survive outside the uterus. "The expression levels of VEGFA and p-p65 proteins decreased significantly in the abortion group compared with the control group (P < 0.01), while miR-381-3p knockdown increased the expression levels of VEGFA and p-p65 proteins than the abortion group." (PMID 40585325, 2025). "In our study, miR-381-3p was highly expressed in the placental tissue of the abortion mouse model and bound to VEGFA." (PMID 40585325, 2025). "Based on miRNA databases, miR-381-3p, which is highly expressed in abortion mice, may bind to vascular endothelial growth factor A (VEGFA)." (PMID 40585325, 2025). "It has been reported that the VEGFA expression decreases in the endometrial tissue of patients with idiopathic recurrent abortion during the peri-implantation period, which may be related to the downregulation of angiogenic cytokines, including IL-2, IL-6, and IL-8." (PMID 40585325, 2025).
biliary atresia (5 papers, 2017 to 2023). A rare, biliary tract disease characterized by progressive obliterative cholangiopathy of the intra- and extrahepatic bile ducts, occurring in the embryonic/ perinatal period, leading to severe and persistent neonatal jaundice and acholic stool. "Previous studies have suggested an association between vascular endothelial growth factor A (VEGFA) rs3025039 polymorphism and biliary atresia (BA)." (PMID 36474631, 2022).
cervical adenocarcinoma (5 papers, 2006 to 2022). An adenocarcinoma arising from the cervical epithelium. "Using HeLa cervical adenocarcinoma cells, we found that seminal plasma (SP) induced the expression of the inflammatory enzymes, prostaglandin endoperoxide synthase (PTGS1 and PTGS2), cytokines interleukin (IL) -6, and -11 and vascular endothelial growth factor-A(VEGF-A)." (PMID 22442729, 2012).
chronic asthma (5 papers, 2013 to 2025). An asthma that is characterized by the development of persistent airway inflammation and recurrent attacks of breathlessness and wheezing, which vary in severity and frequency. "Other studies with PA-treated animals have demonstrated decreased expression of IL-4, IL-5, IL-13, vascular endothelial growth factor A (VEGFA), and transforming growth factor (TGF)-β1 in acute and chronic asthma models." (PMID 32759635, 2020).
E. coli infection (5 papers, 2016 to 2025). "Meningitic E. coli infection can induce VEGFA, PDGFB, and ANGPTL4 expression, aggravating infection-dependent BBB dysfunction." (PMID 38233877, 2024). "Similarly, meningitic E. coli infection significantly upregulates VEGFA expression, which in turn negatively regulates TJ protein expression to increase BBB permeability via the TLR2-MAPK-ERK1/2 pathway." (PMID 38233877, 2024). "Moreover, meningitic E. coli infection led to substantial production of proinflammatory cytokines and chemokines, which also promoted the upregulation of VEGFA and Snail-1, further accelerating the BBB disruption." (PMID 27588479, 2016). "In this study, E. coli infection up-regulated key genes in the Th17 cell differentiation pathway, including FOS, VEGFA, IL12RB2, IFN-ALPHA-8, and IFN-ALPHA-13, indicating widespread activation of the immune system." (PMID 39707535, 2024). "So far, VEGFA and its receptor VEGFR have attracted great attention for their roles in tumor angiogenesis and anti-angiogenesis therapy, but their functions in meningitic E. coli infection remain little investigated." (PMID 27588479, 2016). "Therefore, we hypothesized that VEGFA, PDGFB, and ANGPTL4 may be the potential target genes of Egr-1 in meningitic E. coli infection of hBMEC." (PMID 38233877, 2024).
hemorrhagic fever (5 papers, 2009 to 2021). An infectious disease caused by certain viruses or bacteria that can damage the walls of tiny blood vessels, making them leak, and can hamper the blood's ability to clot and cause severe, life-threatening illness. "The levels of vascular endothelial growth factor-A (VEGF) were estimated in 102 serum samples from 63 hospitalized Greek patients with hemorrhagic fever with renal syndrome (HFRS) caused by Dobrava/Belgrade virus." (PMID 24335780, 2013).
joint disease (5 papers, 2013 to 2022). "Previous research studies have reported that other protein biomarkers implicated in the pathophysiology of joint disease, such as vascular endothelial growth factor-A (VEGF-A) and matrix metalloproteinase 3 (MMP3), are also correlated with disease activity." (PMID 23585841, 2013).
mastitis (5 papers, 2016 to 2025). Inflammation of breast tissue during lactation or postpartum due to an obstructed duct or infection. "In both S. aureus-positive and S. chromogenes-positive cows, the DE snoRNAs were correlated with several immune and inflammatory genes (e.g., IL1R, IL18R1, STAT3, NFKB2, MYD88, VEGFA and CD40), all of which have been reported in several studies to be associated to mastitis." (PMID 40936092, 2025).
Ovarian cyst (5 papers, 2017 to 2022). The presence of one or more cysts of the ovary. "Excess VEGFA levels might be related to ovarian hyperstimulation and the formation of multiple ovarian cysts." (PMID 29490689, 2018). "Surprisingly, we found that VEGFA and IL8 were both highly expressed on the inner surface of ovarian cysts using IF, while no localised specific expression was observed in the control and eutopic endometria." (PMID 35039492, 2022).
Shock (5 papers, 2008 to 2024). The state in which profound and widespread reduction of effective tissue perfusion leads first to reversible, and then if prolonged, to irreversible cellular injury. "Once bacterial dose and infusion-rate optimization was achieved, all sheep developed septic shock (as per Sepsis 3 criteria) within 12 h of completion of E. coli infusion, with corresponding increases in the vasopressor requirement (VDI) and cytokines (IL-6, IL-8, IL-10, and VEGFA)." (PMID 39467921, 2024).
silicosis (5 papers, 2020 to 2025). Silicosis is a respiratory disease caused by breathing in (inhaling) silica dust. "Manipulating VEGFA inhibits fibrosis factor release, suppressing the expression of TGF-β and α-SMA in the lung tissue of rats with silicosis." (PMID 37381044, 2023). "Further researches in vivo will be necessary to clarify the precise regulation of VEGFA and FGFR1 by miR‐503 in silicosis." (PMID 33135394, 2020). "Besides, we found that the protein expression levels of VEGFA and FGFR1 were significantly up‐regulated in the lung tissues of silica‐treated mice, and overexpression of miR‐503 in a mouse model of silicosis efficiently suppressed these two targets." (PMID 33135394, 2020).
spondyloarthritis (5 papers, 2008 to 2025). "Vascular endothelial growth factor-A (VEGF-A) plays a pivotal role in inflammatory rheumatic diseases, including spondyloarthritis (SpA)." (PMID 40487799, 2025).
ZIKV infection (5 papers, 2017 to 2023). "Importantly, levels of monocyte chemoattractant protein 1 (MCP-1), IL-1RA, and vascular endothelial growth factor A (VEGF-A) were affected by both CD14+ monocyte depletion and ZIKV infection." (PMID 29600283, 2018).
alcoholism (4 papers, 2022 to 2025). "The impact of alcohol dependence on plasma concentrations of VEGFA and chemokines was studied in the total sample using Mann–Whitney U-test." (PMID 35625687, 2022). "GFR, absolute value, hsCRP, PlGF, log VEGFA, log Lipocalin2NGAL, and log PAI1 were significantly higher and HOMA‐IR was significantly lower in the alcohol use group in comparison with the control group (p < .05)." (PMID 37707300, 2023).
aneurysmal disease (4 papers, 2021 to 2024). "Some studies suggest that aneurysmal disease requires anti-VEGFA therapy to reduce inflammation and tissue destruction, whereas recent studies suggest that promoting VEGFA expression may contributed to accelerating endothelialization after stent implantation." (PMID 35711443, 2022).
Aortic dissection (4 papers, 2021 to 2024). Aortic dissection refers to a tear in the intimal layer of the aorta causing a separation between the intima and the medial layers of the aorta. "In the context of aortic dissection, there may be interactions and functional associations between VEGFA and PPARG." (PMID 38567101, 2024). "As a transcription factor, PPARG may modulate the expression of VEGFA, thereby influencing angiogenesis and vascular permeability, further impacting the development and progression of aortic dissection." (PMID 38567101, 2024). "Additionally, in inflammation and immune responses, VEGFA and PPAR may mutually influence each other through the regulation of inflammation and immune responses, affecting the pathological processes of aortic dissection." (PMID 38567101, 2024).
Barrett esophagus (4 papers, 2007 to 2026). Esophageal lesion lined with columnar metaplastic epithelium which is flat or villiform. "The concurrent use of VEGFA-guided NIR fluorescence molecular endoscopy and high-definition white-light endoscopy, following tracer administration, can be used to detect dysplastic and early cancerous lesions in patients with Barrett’s oesophagus." (PMID 35937852, 2022).
Cachexia (4 papers, 2010 to 2021). Severe weight loss, wasting of muscle, loss of appetite, and general debility related to a chronic disease. "Previous studies concerning cachexia in gastrointestinal cancer revealed that other pro-inflammatory cytokines, such as IL-8 and, probably, vascular endothelial growth factor-A (VEGF-A) and midkine, might be involved in the process of cachexia." (PMID 20920199, 2010).
cocaine addiction (4 papers, 2022 to 2023). "Upstream non-key genes (FGF2, VEGFA, and IL1B) affect the expression of downstream genes in this pathway, while MAP2K2 regulates ERK through phosphorylation, thereby affecting cocaine addiction." (PMID 37469839, 2023).
colon adenoma (4 papers, 2013 to 2023). An adenoma that arises from the colon. "This antibody is specific for vascular endothelial growth factor A (VEGFA), which is upregulated in colonic adenomas." (PMID 37835489, 2023).
erythroleukemia (4 papers, 2016 to 2022). Acute erythroid leukemia characterised by the presence of at least 50% erythroid precursors and at least 20% myeloblasts in the bone marrow. "In accordance, the methylation of the linked ESSE site was negatively correlated with VEGFA expression in ES, normal T and B cells, T cell leukemia (Jurkat) and erythroleukemia (K562) cells." (PMID 26886256, 2016).
follicular thyroid cancer (4 papers, 2015 to 2021). "In accordance with previous studies that investigated other follicular thyroid cancer cells on the RPM, VEGFA expression was somewhat increased in MCS cells after three days." (PMID 32033410, 2020).
IgA nephropathy (4 papers, 2013 to 2023). "Notably, one study found that patients with IgA nephropathy with high urinary VEGFA levels had a poor prognosis for renal replacement therapy." (PMID 37266443, 2023).
keratoconus (4 papers, 2022 to 2024). A degenerative, structural disorder of the eye, characterized by a cone-shaped protrusion of the cornea. "The expression of CCR2, CDKN1A, HSPA5, MAPK8IP1, PPP1R15A, and VEGFA in individuals with keratoconus was significantly different from that in control subjects." (PMID 38830963, 2024).
non-melanoma skin carcinoma (4 papers, 2012 to 2022). "Differential genetically determined expression of transforming growth factor-β (TGF-β pathway and of vascular endothelial growth factor-A (VEGF-A) might modulate the molecular “milieu” involved in the etio-pathogenesis of non-melanoma skin cancer (NMSC)." (PMID 35886018, 2022).
ocular infection (4 papers, 2011 to 2025). "Our study suggests that the preeminent source for VEGF-A during acute ocular infection is HSV-1 infected cells on the basis co-localization of VEGFA-GFP reporter with HSV-1 antigen and experiments using HSV-1 infected cell-specific deletion of VEGF-A." (PMID 21998580, 2011).
ocular vascular disorder (4 papers, 2016 to 2022). A disorder that is caused by pathologic changes in the ocular vasculature. "Of note, VEGFA is a target for several antibody, protein and oligosaccharide agents, which are currently in phase 2, 3 and 4 clinical trials, including for several ocular vascular disorders." (PMID 35654884, 2022).
prediabetes (4 papers, 2014 to 2025). "Results of this study and previous results showed an overexpression of Toll-like receptors (TLR4 and 6), Janus kinase 2 (JAK2) and Vascular endothelial growth factor A (VEGFA) in prediabetes patients." (PMID 37457235, 2023).
primary myelofibrosis (4 papers, 2012 to 2021). Myelofibrosis with myeloid metaplasia is a myeloproliferative disease with annual incidence of approximately 1 case per 100,000 individuals and age at diagnosis around 60 (an increased prevalence is noted in Ashkenazi Jews). "We evaluated the association of VEGFA rs3025039 polymorphism with clinical co-variates and outcomes in 849 subjects with primary myelofibrosis (PMF) and 250 healthy controls." (PMID 34440447, 2021). "VEGFA is known to exert a major influence on the development and progression of primary myelofibrosis (PMF)." (PMID 34778698, 2021).
thyroid nodule (4 papers, 2016 to 2024). A small circumscribed mass in the THYROID GLAND that can be of neoplastic growth or non-neoplastic abnormality. "The aim of the current study was to assess the expression of vascular endothelial growth factor A (VEGF-A) and VEGF-C on the mRNA level in FNAB washouts in case of benign and malignant thyroid nodules and to evaluate the diagnostic value of these markers of malignancy." (PMID 26900960, 2016).
vitiligo (4 papers, 2023 to 2025). Generalized well circumscribed patches of leukoderma that are generally distributed over symmetric body locations and is due to autoimmune destruction of melanocytes. "The five key target genes (AKT1, VEGFA, ESR1, IL2, and MPO) identified by the compound–target network were closely related to the pathogenesis and/or treatment of vitiligo." (PMID 38659590, 2024).
alcohol addiction (3 papers, 2016 to 2022). "Plasma levels of SDF-1, eotaxin and VEGFA were found to be significantly correlated with alcohol addiction severity based on alcohol criteria (rho = 0.211, p < 0.048; rho = 0.250, p < 0.018; rho = 0.234, p < 0.027, respectively)." (PMID 35625687, 2022).
Alport syndrome (3 papers, 2015 to 2018). A rare renal disease characterized by glomerular nephropathy with hematuria progressing to end-stage renal disease (ESRD), frequently associated with sensorineural deafness, and occasionally with ocular anomalies. "This study explored the expression of VEGFA in the glomeruli and its accumulation in the glomerular basement membrane (GBM) and their relationship with podocyte injury and proteinuria in Alport syndrome (AS)." (PMID 26274923, 2015).
amenorrhea (3 papers, 2013 to 2025). The absence of menses in a woman who has achieved reproductive age. "As a result, the symptoms of amenorrhea could be potentially relieved by the increase of VEGFA, which provides the potential pharmacological mechanism for SWT to treat amenorrhea." (PMID 24223693, 2013). "Previous research showed that there was a significant reduction in the expression of VEGFA for women with amenorrhoea, whereas our study concerning differentially expressed genes showed that the mRNA of VEGFA was significantly up-regulated under the influence of SWT." (PMID 24223693, 2013).
aortic aneurysm (3 papers, 2019 to 2022). A ruptured aneurysm located in the wall of the proximal portion of the descending aorta proceeding from the arch of the aorta. "Such upregulation translated into higher hypoxia-inducible factor 1 (HIF-1) and vascular endothelial growth factor A (VEGF-A) expression and dysregulated HIF-1α/VEGF signaling was associated with aortic aneurysm progression." (PMID 34572356, 2021).
bone sarcoma (3 papers, 2017 to 2023). A sarcoma that arises from the bone.
bronchitis (3 papers, 2021 to 2022). An acute or chronic inflammatory process affecting the bronchi. "The activation of the VEGFA pathway explains the hyperproduction of mucus in the bronchitis phenotype, since VEGFA was originally described as a factor, increasing vascular permeability." (PMID 33805156, 2021).
cerebral small vessel disease (3 papers, 2020 to 2023). Cerebral small vessel disease is the term currently used to pathological processes that affect the brain parenchymal circulation (arterioles, capillaries, and veins). "In humans, increased VEGFA plasma levels in cerebral small vessel disease patients were associated with increased blood–brain barrier permeability in the normal appearing white matter." (PMID 37550790, 2023). "Our results support a role of VEGFA expression in cerebral hypoperfusion as seen in cerebral small vessel disease." (PMID 37550790, 2023). "Additionally, human blood plasma VEGFA levels were measured and correlated to blood–brain barrier permeability in normal-appearing white matter and white matter lesions of cerebral small vessel disease patients and controls." (PMID 37550790, 2023).
clostridium difficile infection (3 papers, 2019 to 2024). Symptomatic infection due to the spore-forming bacterium clostridium difficile. "In cases of Clostridium difficile infection (CDI), the two major toxins produced (TcdA and TcdB) increase expression of vascular endothelial growth factor A (VEGF-A) in gut epithelial cells." (PMID 33221945, 2021).
demyelinating disease (3 papers, 2015 to 2023). A broad group of disorders that affect the myelin sheaths that cover the neurons. "Another NMO marker of BBB breakdown, vascular endothelial growth factor-A (VEGF-A), has been implicated in promoting BBB breakdown in demyelinating disorders." (PMID 26500654, 2015).
enteritis (3 papers, 2022 to 2024). Inflammation of the small intestine.
femoral neck fracture (3 papers, 2017 to 2026). Fractures of the short, constricted portion of the thigh bone between the femur head and the trochanters. "Femoral neck fracture (FHF) group showed the raise of VEGFA associated interactions in the crosstalk between neutrophil and endothelium, while the TGFB associated interaction strength in the crosstalk between neutrophil and fibroblasts was not significant." (PMID 40169566, 2025).